RNU2-68P (RNA, U2 small nuclear 68, pseudogene)
Gene: Small nuclear RNA gene on chromosome X (72,376,979 to 72,377,169, reverse strand). Ensembl gene ENSG00000222810.
Homologues: Orthologues: chimpanzee U2 (98% identical), macaque U2 (97% identical), rat LOC120101104 (67% identical). Paralogues in human: U2 (87% identical), RNU2-6P (85% identical), U2 (84% identical), RNU2-26P (81% identical), RNU2-2 (81% identical), RNU2-3P (81% identical), RNU2-57P (81% identical), RNU2-59P (81% identical), RNU2-4P (80% identical), RNU2-39P (80% identical), RNU2-61P (79% identical), RNU2-48P (78% identical), and 67 more.